PVT1 (Pvt1 oncogene)
Diseases named in the same sentence as PVT1 in open-access papers (continued):
Sharing a sentence is not in itself a finding about the gene and the disease.
tumor (continued). "As a type of tumor molecular gene, PVT1 is abnormally expressed in multiple types of tumors and can therefore simultaneously regulate multiple tumors." (PMID 36164442, 2022). "Given the diversity of proposed functional elements and mechanisms, additional studies are required to deconvolve the oncogenic and tumor‐suppressive elements in the PVT1 locus." (PMID 34668345, 2022). "We also detected elevated expression of PVT1 in most tumor samples and gains in the MYC/PVT1 genomic locus in a third of the samples." (PMID 36139061, 2022). "Conversely, reducing PVT1 levels robustly abrogates metastatic behavior and tumor cell dissemination in cell lines and syngeneic transplantation models in vivo." (PMID 35820706, 2022). "A previous study reported that PVT1 was up-regulated in BC tissues when compared with the normal tissues and its silencing repressed tumor growth." (PMID 35027621, 2022). "Genes located in this region, including MYC, POU5F1B and PVT1, were notorious for tumor progression." (PMID 35493106, 2022). "Invasion and metastasis are multistep and multilevel regulatory processes, and lncRNA PVT1 can regulate the complex process of tumor metastasis through miRNA." (PMID 36379920, 2022). "For example, long non-coding RNA PVT1 is reported to be closely related to autophagy and has been proved to affect tumor autophagy via miR-365/ATG3, miR-20a-5p/ULK1, miR-619-5p/ATG14 or multiple axes." (PMID 34823534, 2021). "Lung and liver samples were obtained to evaluate tumor metastasis, and the number of metastatic cells in liver and lung were significantly reduced by si-PVT1." (PMID 34922601, 2021). "In vitro and in vivo experiments revealed that reduced FOXM1 level can rescue the effects induced by increased circular PVT1 on tumor viability." (PMID 33391456, 2021). "Corresponding with the dysregulation in RCC tumor samples, PVT1 is overexpressed in RCC cells as well." (PMID 33947142, 2021). "On the other hand, a recent study demonstrated that PVT1 can also act as a tumor suppressor; thus, PVT1 can either promote or inhibit Myc activity depending on cellular context." (PMID 33239359, 2021). "In the study, gain of MYC or the PVT1/CCDC26/GSDMC region alone did not result in tumourigenesis, but co-amplification of MYC and PVT1/CCDC26/GSDMC resulted in a pro-tumour transformation." (PMID 33499210, 2021). "LncRNA PVT1 can promote the malignant phenotype of tumor cells by regulating DNA rearrangement and interacting with other oncogenes." (PMID 32960485, 2021). "As expected, in vivo xenograft experiments showed that PT2385 significantly inhibited tumor growth coupled with decreased PVT1 expression." (PMID 34321604, 2021). "In most cases, lncRNA PVT1 is regarded as a tumor promoter in various malignancies which increases the malignant phenotype of tumor cells." (PMID 34898354, 2021). "In the current research, expression level of PVT1, its functional impact on the proliferation, apoptosis, and metastasis of CC cells in vitro, and on tumor growth in vivo, as well as the possible regulatory mechanisms were investigated." (PMID 33817293, 2021). "The Kaplan-Meier survival analysis demonstrated that high-PVT1 expression group showed greater tumor size, increased lymph node metastasis, and distant metastasis compared with low-PVT1 expression group." (PMID 34321604, 2021). "Analysis of The Cancer Genome Atlas database found that out of the tumours which displayed an 8q24 copy-number increase, 97% showed a gain of both PVT1 and MYC, while less than 1% of tumours showed an increase in copy number of MYC alone." (PMID 33499210, 2021). "We also conducted rescue assays to validate circular PVT1 impeded tumor growth by targeting to FOXM1." (PMID 33391456, 2021). "Cell cycle and proliferation: PVT1 downregulation inhibited tumor growth and expansion both in vitro and in vivo and induced cell cycle arrest at the G1 phase." (PMID 34322395, 2021).
tumor (continued). "Orthotopic mouse models were established to evaluate the influence of PVT1 on tumor growth and metastasis in vivo." (PMID 34922601, 2021). "PVT1 knockdown exerted tumor suppressor role in CC progression via the miR-503/ARL2 axis, at least in part." (PMID 33817293, 2021). "In this study, we observed an obvious upregulation of PVT1 expression in CC tissues and cell lines, and silencing of PVT1 restricted cell proliferation, migration and invasion in vitro, as well as inhibited tumor growth in vivo." (PMID 33817293, 2021). "High expression of PVT1 was associated with TNM stage, fuhrman grade, lymph node involvement, and tumor dimension." (PMID 33842553, 2021). "PVT1 silencing reduced tumor migration and invasiveness via sponging miR-128-3p, which inhibited GREM1 and inhibition of the BMP signaling pathway." (PMID 34322395, 2021). "The biological significance of PVT1 was first explored using human tumor tissues and the matched adjacent normal tissues." (PMID 34321604, 2021). "Specifically, PVT1 expression level had a significant correlation with tumor size, TNM stage, and lymphatic metastasis in patients with PTC." (PMID 34927541, 2021). "As a result, we detected significant differences between PVT1 polymorphisms and LNM and tumor stage in male or female GC subgroup." (PMID 35049170, 2021). "The expression level of PVT1 was significantly related to tumor size, TNM stage, and lymph node metastasis in patients with PTC." (PMID 34927541, 2021). "To further explore the significance of PVT1 expression in BC, we analyzed PVT1 expression in relationship to tumor stages and found that the plasma levels of PVT1 were significantly higher in patients with stage III and IV than those with stage I and II." (PMID 34922601, 2021). "PVT1 was reported to regulate cell proliferation and tumor growth in triple-negative BC through KLF5/ beta-catenin signaling." (PMID 34922601, 2021). "In osteosarcoma (OS), it was found that lncRNA PVT1 expression was upregulated in OS tissues and cells and was significantly related with clinical stage, tumor size, and prognosis of patients with OS." (PMID 34188972, 2021). "LncRNA PVT1 was corroborated to be a potential therapeutic target for CC, and PVT1 proved its tumor-promoting role by negatively modulating miR-424." (PMID 33817293, 2021). "In the present study, we revealed that the expression of PVT1 in STAD was significantly higher in tumor tissues than in adjacent normal tissues." (PMID 34876056, 2021). "The results showed that the expression of PVT1 in our cohort was significantly increased in the tumor tissues compared to the adjacent normal tissues (p < 0.001)." (PMID 34876056, 2021). "As direct targets of PVT1, UPF1 and miR-128-3p mediate the roles of PVT1 in tumor proliferation and metastasis." (PMID 34922601, 2021). "In our study, in vitro and in vivo experiments both verified that PVT1 significantly promoted malignant biological behavior of ccRCC cells, especially tumor angiogenesis." (PMID 34321604, 2021). "Invasion and metastasis: PVT1 induced tumor invasiveness via modulating several target molecules and signaling pathways." (PMID 34322395, 2021). "Specifically, the tumour volume curve and tumour weight of sh‐PVT1 or sh‐AGO1 were significantly decreased compared with those in relative scramble." (PMID 34288373, 2021). "Multiple miRNA response elements have been found on PVT1, and PVT1 can bind to specific miRNAs, thereby silencing them and upregulating the expression of certain proteins, ultimately affecting tumor cell proliferation, invasion, and drug resistance." (PMID 34336125, 2021). "Inhibition of PVT1 using PVT1 ASOs significantly suppressed tumor cell growth and invasion in vitro and in vivo." (PMID 33076512, 2020). "For example, the lncRNA PVT1 is up-regulated in RB tissues and silencing PVT1 can suppress the tumor growth." (PMID 32117995, 2020).
tumor (continued). "Functionally, ALKBH5-mediated PVT1 upregulation promoted the OS cell proliferation in vitro and tumor growth in vivo." (PMID 32021563, 2020). "PVT1 expression was induced by HIF-1α in tumor-infiltrating G-MDSC, which experiment hypoxic conditions." (PMID 32228602, 2020). "Of note, a number of lncRNAs with broad oncogenic (SNHG12, CASC9, LUCAT1 and PVT1) or tumor suppressor (such as TINCR) function were also identified to be differentially expressed in cSCC25–28." (PMID 32108138, 2020). "We next further sought to elucidate the biological role of PVT1 in NPC tumorigenesis, and found that PVT1 knockdown significantly inhibited NPC tumor growth in mice in the PVT1 silenced group relative to the control group." (PMID 31320749, 2020). "By contrast, other studies demonstrated that co-amplified MYC and PVT1 cooperatively promote tumor progression." (PMID 32235890, 2020). "LncRNA PVT1 expression was positively correlated with larger tumor size, deeper wall invasion, lymph node metastases, and short survival duration." (PMID 33076512, 2020). "This study extends our understanding of the function of PVT1 in PC and provides novel insight into the role of lncRNAs in tumor biology." (PMID 32499447, 2020). "Targeting PVT1 using PVT1 ASOs suppressed tumor proliferation and invasion in both vitro and vivo, thus provide a novel therapeutic strategy for GAC." (PMID 33076512, 2020). "The tumor weight was measured at the end, and the data indicated that the tumor weight was weaker in sh-PVT1-injected groups relative to sh-NC groups." (PMID 32624708, 2020). "PVT1 functions as an oncogene by inhibiting the apoptosis of tumor cells, promoting cell proliferation, and affecting tumor invasion and metastasis generation." (PMID 32194993, 2020). "Functional experiments, including colony formation and invasion assays, were performed to evaluate the effects of PVT1 ASO inhibition of PVT1 in vitro; patient-derived xenograft models were used to evaluate the anti-tumor effects of PVT1 ASOs in vivo." (PMID 33076512, 2020). "We first evaluated the genomic alteration of PVT1 in GAC tissues from TCGA dataset across different tumor types." (PMID 33076512, 2020). "The 8q24 germline variant is located within PVT1, a candidate oncogene that is thought to regulate MYC to promote tumor formation." (PMID 33121461, 2020). "High expression of linear PVT1 has been detected in granulocytic myeloid-derived suppressor cells (G-MDSC) from tumor tissues in murine models of Lewis lung carcinoma and colorectal cancer." (PMID 32228602, 2020). "Stomach adenocarcinoma (STAD) (same as GAC) had one of the highest PVT1 alterations among various tumor types, with (about 15% PVT1 amplification); ~70% of STAD cases contained both amplification and duplication." (PMID 33076512, 2020). "Meanwhile, the tumor weight from sh-PVT1 group was significantly lighter than that from the sh-NC group." (PMID 33067424, 2020). "Taken together, the results suggest that PVT1 promoted exosome secretion of PC cells and thus, can expand the understanding of PVT1 in tumor biology." (PMID 32499447, 2020). "RNA scope in situ hybridization was used to analyze PVT1 expression in tumor tissue microarrays (TMAs) of GAC and paired normal tissues from 792 patients." (PMID 33076512, 2020). "It was shown that oncogenic PVT1 interacts with several tumor-suppressive miRNAs, such as miR-133a, miR-214, miR-140, and miR-543; also, inhibition of suppressor miRNAs is one of the modes to enhance the progression of OvCa." (PMID 33238475, 2020). "Using R-Scope ISH, we directly visualized PVT1 expression; it was found mostly in the nucleus of tumor cells but was less enriched in other cell types or stromal cells." (PMID 33076512, 2020). "To further confirm TCGA results, we performed qPCR to measure PVT1 expression in 17 pairs of GAC tumor and normal tissues." (PMID 33076512, 2020).
tumor (continued). "PVT1 expression was highly associated with poor prognosis in GAC patients and targeting PVT1 using PVT1 ASOs was effective at curtailing tumor cell growth in vitro and in vivo." (PMID 33076512, 2020). "The tumor volume, recorded every 4 days at 10 days post-injection, was obviously decreased in sh-PVT1-injected groups relative to sh-NC." (PMID 32624708, 2020). "The previous reports revealed that lncRNA PVT1 was upregulated in tumor tissues compared to adjacent normal tissues in GAC patients and was associated with lymph node metastases and a shorter survival." (PMID 33076512, 2020). "The authors underlined the significance of their findings and measured PVT1 levels in BTC patient specimens and observed high levels of PVT1 in tumor samples associated with an advanced TNM-stage, poorer overall survival and distant metastasis." (PMID 32331331, 2020). "The knockdown of lncRNA Pvt1 significantly reduced the immunosuppressive activity of G-MDSCs such as decreased levels of Arg1 and ROS in G-MDSCs and delayed tumor progression in tumor-bearing mice." (PMID 32443699, 2020). "Whereafter, the expression of PVT1, miR-15a-5p and KIF23 was detected in removed tumor tissues, and we found the expression of PVT1 and KIF23 was significantly declined, while miR-15a-5p expression was strengthened by qRT-PCR analysis." (PMID 32624708, 2020). "Whilst, lncRNA PVT1 has been indicated to function as a tumor promoter that has a significant role in the metastasis in ccRCC." (PMID 33173535, 2020). "Although these results are similar to ours, most of these studies used qPCR to detect PVT1 levels in normal and tumor tissues and the sample sizes were limited." (PMID 33076512, 2020). "Our further experiments of the nude mice animals illustrated that the knockdown of PVT1 inhibited tumorigenicity and lessened tumor volume and weight in vivo." (PMID 33188158, 2020). "In this study, we found that PVT1 expression was upregulated in OS tissues and cells and significantly related with clinical stage, tumor size, and prognosis of patients with OS." (PMID 32021563, 2020). "LncRNA PVT1 is a critical lncRNA that plays an oncogenic role in several tumor types, including GAC." (PMID 33076512, 2020). "This review systematically outlines the manners through which PVT1 affects the development of the tumor via miRNAs." (PMID 31380270, 2019). "It was recently was found that the PVT1 promoter can behave as a tumor suppressor DNA boundary element by competing with the MYC promoter in cis for shared enhancers within the gene locus." (PMID 31508377, 2019). "Effective knockdown of PVT1 in EAC cells using PVT1 ASOs resulted in decreased cell proliferation, invasion, colony formation, tumor sphere formation, and reduced proportion of ALDH1A1+ cells." (PMID 31601234, 2019). "PVT1 involved in tumor proliferation, invasion, migration and apoptosis and played an important role in tumor progression, metastasis and prognosis." (PMID 30083911, 2019). "MYC is an important gene involved in many important processes of tumor progression and is located next to the PVT1 locus." (PMID 31601234, 2019). "In the future, we can interfere with the function of PVT1 in tumor cells using siRNAs or antisense LNA GapmeRs against PVT1." (PMID 31309249, 2019). "Numerous studies have shown that PVT1 can fuse to other genes by translocation in certain tumor tissues." (PMID 31309249, 2019). "We propose a regulatory network that centered on PVT1, analyze the feasibility of using PVT1 as a tumor molecular marker and discuss its potential clinical applications." (PMID 31380270, 2019). "In CRC cells, PVT1 sponged miR-455 and negatively regulated miR-455 expression, which functions as a tumor suppressor in human cancers." (PMID 31744051, 2019). "Interaction between an enhancer region downstream the first transcriptional start site of PVT1 and the PVT1 promoter itself has tumor suppressor activity by reducing MYC transcription." (PMID 30451365, 2019).
tumor (continued). "Further analysis has identified RSPO1, a major regulator of the β-catenin signaling pathway, as a potential contributor to the regulation of Myc-PVT1 in tumor growth." (PMID 31497532, 2019). "For the analysis of clinicopathological characteristics, in Han GC patients, PVT1 expression levels correlated with lymph node metastasis and primary tumor site (P < 0.05)." (PMID 30679629, 2019). "PVT1/miR-190a-5p/miR-488-3p/MEF2C/JAGGED1 pathways were shown to be involved in the promotion of tumor cell proliferation." (PMID 31380270, 2019). "Consistently, IHC showed Bcl2 staining was also strengthened when PVT1 was overexpressed in the orthotopic GC tumor." (PMID 31205469, 2019). "PVT1 also modulates HK2 expression by competitively binding to endogenous miR-143 in tumor cells, which promotes cell proliferation and metastasis by regulating aerobic glucose metabolism." (PMID 31380270, 2019). "A tumor mouse model treated with Pvt1-down-regulating PMN-MDSCs showed reduced growth in the generated tumors and a modest increase in the number of CD8+ T cells producing IFN-γ in lymphatic nodules." (PMID 31404149, 2019). "In contrast to the tumor‐suppressive role of the PVT1 promoter, the PVT1 transcript can act as an oncogene." (PMID 30451365, 2019). "To evaluate the antitumor effect in vivo, we tested anti-tumor effects of PVT1- and YAP1-specific ASOs alone or in combination of PVT1 and YAP1 specific ASOs in JHESO xenograft mice model." (PMID 31601234, 2019). "We found that the expression of Pvt1 was higher in G-MDSCs isolated from tumor tissues of Lewis-bearing mice than in spleens from wild-type mice." (PMID 30925926, 2019). "G-MDSCs isolated from tumor tissues of tumor-bearing C57BL/6 mice were transfected with si-Pvt1 in vitro." (PMID 30925926, 2019). "A recent study shows that knock-down of PVT1 can increase the radiosensitivity of the tumor, suggesting its role as an oncogene to promote tumor progression." (PMID 31380270, 2019). "Pvt1 regulates the immunosuppression activity of granulocytic myeloid-derived suppressor cells (G-MDSCs), which is a subgroup of MDSCs, and Pvt1 is up-regulated by HIF-1α under hypoxia conditions in tumor-bearing mice." (PMID 31850189, 2019). "PVT1 also plays a role in regulating the apoptosis of tumor cells through activating c-MET/PI3K/AKT and co-activator-associated arginine methyltransferase 1 (CARM1) signaling pathways by sponging miR-152 and miR-424-5p, respectively." (PMID 31380270, 2019). "High expression of PVT1 in tumor cells can be used as a competing endogenous RNA sponge to adsorb miR-199a-5p or miR-186 and subsequently upregulate the expression of HIF-1α." (PMID 31309249, 2019). "Plasmacytoma variant translocation 1 (PVT1) lncRNA is increased in HCC tissues and associated with tumor size, histological differentiation grade, and advanced TNM stage." (PMID 31640265, 2019). "Tumor growth was significantly reduced in mice injected with G-MDSCs transfected with si-Pvt1 (si-Pvt1 group) compared with mice injected with G-MDSCs transfected with the negative control (si-NC group)." (PMID 30925926, 2019). "In CRC patients, upregulated PVT1 positively correlates with cell proliferation, invasion, tumor stages, and lymph node metastasis." (PMID 31744051, 2019). "The PVT1/miR-497/HK2 axis which regulates tumor cell energy metabolism is another important pathway that promotes tumor cell proliferation." (PMID 31380270, 2019). "LncRNA PVT1 significantly promoted autophagy and subsequent proliferation of tumor cells through acting as a ceRNA to target ATG3 by sponging microRNA-365 in HCC." (PMID 31761783, 2019). "Through either amplification process, PVT1 will generate new fusion genes, and these abnormal changes in the gene replication process play an important role in tumor development." (PMID 31309249, 2019).